ELOVL1 (ELOVL fatty acid elongase 1)
Diseases named in the same sentence as ELOVL1 in open-access papers (continued):
Sharing a sentence is not in itself a finding about the gene and the disease.
melanoma (1 paper, 2025). A malignant, usually aggressive tumor composed of atypical, neoplastic melanocytes. "Through mouse models of PDAC and melanoma, and ACT of antigen-specific CD8+ T cells, we demonstrate that Elovl1 deficiency amplifies T cell antitumoural activity when combined with anti-PD-1 treatment." (PMID 40065102, 2025). "Accordingly, Elovl1 inactivation in adoptively transferred T cells combined with anti-PD-1 showed therapeutic efficacy in resistant pancreatic and melanoma tumours." (PMID 40065102, 2025). "Finally, ELOVL1 in CD8+ T cells correlated with anti-PD-1 response in patients with melanoma." (PMID 40065102, 2025). "in vivo, Elovl1 deletion and ICB therapy synergize to overcome immunotherapy resistance in PDAC and melanoma preclinical models." (PMID 40065102, 2025). "CD8+ TILs showed significantly lower ELOVL1 expression in both patients with PDAC and melanoma responding to anti-PD-1 therapy compared with nonresponding or resistant patients." (PMID 40065102, 2025). "Furthermore, in scRNA sequencing of melanoma, exhausted/effector CD8+ TILs showed significantly lower ELOVL1 expression in responders than in nonresponders and resistant patients, suggesting that ELOVL1low TILs are more effective in synergizing with anti-PD-1 treatment than ELOVL1high TILs." (PMID 40065102, 2025). "Finally, given the paucity of available biopsies from patients with PDAC under anti-PD-1 treatment, we could not validate the role of ELOVL1 in human PDAC cohorts and therefore relied on a dataset of patients with melanoma, where anti-PD-1 is a first-line treatment." (PMID 40065102, 2025).
ovarian carcinoma (1 paper, 2023). A malignant neoplasm originating from the surface ovarian epithelium. "SCD1 and FASN expressions were higher and ELOVL1–6 and FADS1 expressions were lower in ovarian cancer tissue, while ACC1 and FADS2 were unchanged." (PMID 37712874, 2023). "To determine whether fatty acid metabolism is altered in ovarian cancer tissue, we first evaluated the gene expression of fatty acid synthases (ACC1, FASN), fatty acid desaturases (SCD1, FADS1, FADS2) and fatty acid elongase 1–6 (ELOVL1–6) in ovarian tumor tissues and normal ovarian tissues." (PMID 37712874, 2023).
pancreatic cancer (1 paper, 2025). "Together, these data indicate that Elovl1 deletion in CD8+ T cells synergizes with anti-PD-1 treatment to overcome immunotherapy resistance in our pancreatic cancer model." (PMID 40065102, 2025). "In conclusion, genetic ablation of Elovl1 combined with anti-PD-1 treatment improves CD8+ T cell activation and functionality in the immune-suppressive microenvironment of pancreatic cancer." (PMID 40065102, 2025).
retinitis pigmentosa (1 paper, 2017). Retinitis pigmentosa (RP) is an inherited retinal dystrophy leading to progressive loss of the photoreceptors and retinal pigment epithelium and resulting in blindness usually after several decades. "Slc4a4 has also been linked to retinitis pigmentosa (RP) type 17 and Elovl1 is an endogenous inhibitor of the visual cycle enzyme RPE65, defects in which cause RP type 2054–56." (PMID 29116131, 2017).
Spastic paraplegia (1 paper, 2019). Complete loss of the ability to move the lower limbs accompanied by spasticity of the lower limbs. "Elovl1−/−Tg(IVL‐Elovl1) mice exhibited myelin thinning, which is related to the hypomyelination seen in patients with the ELOVL1 mutation; however, these mice did not exhibit any noticeable signs of movement abnormalities related to spastic paraplegia." (PMID 32123819, 2019).
steatosis (1 paper, 2020). Increased lipid within the cytoplasm of cells. "Collectively, our previous study and current data indicate the development of severe steatosis was closely related to the genes involved in lipid synthesis, packaging, secretion, transportation, deposition or metabolism, including FADS, ELOVL1, ELOVL5, and ACAT2." (PMID 32054153, 2020).
viral infection (1 paper, 2022). "Here, the elongation of LCFAs to VLCFAs by the enzyme ELOVL1 and the degradation of VLCFAs by peroxisomal β-oxidation may represent critical steps for VLCFA homeostasis and availability during viral infection." (PMID 36085307, 2022).
tumor (12 papers, 2019 to 2025). "Considering that we performed CROP-seq in the primary tumour, we further characterized the impact of Elovl1-deficient OT-I T cells in the same tissue." (PMID 40065102, 2025). "Elovl1-deficient T cells increased mitochondrial fitness and fatty acid oxidation, thus withstanding the metabolic stress imposed by the tumour microenvironment." (PMID 40065102, 2025). "Moreover, Elovl1-deficient pmel-1 T cells showed higher Tpex and Tcm differentiation in the tumour and spleen, respectively, as well as increased expression of co-inhibitory modules." (PMID 40065102, 2025). "In this work, we identified ELOVL1 as a metabolic checkpoint promoting the reprogramming of cellular metabolism, and leading to increased fitness and tumour control in synergy with anti-PD-1." (PMID 40065102, 2025). "What is interesting, although in para-tumor tissue whole group of VLCSFAs was higher than in healthy tissue we didn’t detect significantly higher gene expression of ELOVL1 in para-tumor tissue compared to healthy tissue." (PMID 39145825, 2025). "Pretreatment with C24:0 or lovastatin prevented the beneficial effect mediated by Elovl1 deletion on tumour growth control." (PMID 40065102, 2025). "The same results were obtained when analyzing the enhancing tumor region where ELOVL1 (p = 0.0013) and ELOVL7 (p = 0.004) expressions were lower than in the peritumoral area." (PMID 36291290, 2022). "In the tumor core, the expression of ELOVL1 was positively correlated with cigarette packs smoked per year and negatively correlated with age, body weight, and BMI." (PMID 36291290, 2022). "The ELOVL2 expression in the tumor core was positively correlated with the ELOVL1 expression from the enhancing tumor region." (PMID 36291290, 2022). "The ELOVL1 expression in the tumor core relative to the peritumoral area was greater in the women (p = 0.0016) and lower in the men (p = 0.0016)." (PMID 36291290, 2022). "In the tumor core, the expression of ELOVL1 (p = 0.04) and ELOVL7 (p = 0.013) was lower than in the peritumoral area." (PMID 36291290, 2022). "Of note, Elovl1, which was enriched in the liver in the initial screening, proved to be a highly efficient target to combat primary tumour and peritoneal metastasis, supporting the relevance of our multi-dimensional approach in identifying promising targets with enhanced systemic fitness." (PMID 40065102, 2025). "Last, to confirm a direct role of VLCFAs and cholesterol in the phenotype modulations occurring in Elovl1-deficient CD8+ T cells, we performed ACT of sgElovl1 OT-I T cells pretreated with lignoceric acid or lovastatin in KPC_OVA tumour-bearing mice and treated them with anti-PD-1." (PMID 40065102, 2025). "Notably, in patients undergoing anti-PD-1 therapy, low ELOVL1 expression in CD8+ tumour-infiltrating lymphocytes (TILs) correlated with a favourable treatment response." (PMID 40065102, 2025). "Elevated expression of ELOVL1 and ELOVL3 in this tumor type is associated with a poorer prognosis." (PMID 37239243, 2023). "In conclusion, in terms of clinical applications, ELOVL1 was closely related to tumor grade and tumor T stage and might predict the prognosis of HCC patients." (PMID 35912257, 2022). "Additionally, the ELOVL1 expression in the tumor core was positively correlated with ELOVL4, ELOVL5, ELOVL6, and ELOVL7 expressions." (PMID 36291290, 2022). "In addition, high ELOVL1 expression was remarkably associated with advanced TNM stage and tumor grade." (PMID 35912257, 2022). "Furthermore, the high expression of ELOVL1 showed insensitive to immunotherapy and was related to microsatellite instability (MSI) and tumor mutational burden (TMB)." (PMID 35912257, 2022). "Additionally, ELOVL1 was negatively related to tumor purity (R = −0.11, P = 0.035) in HCC." (PMID 35912257, 2022).
tumor (continued). "The univariate Cox analysis showed that tumor stage (HR = 1.144, p < 0.001), T stage (HR = 1.219, p < 0.001), metastasis (HR = 1.273, p =0.010), N (regional lymph node) (HR = 1.232, p =0.024), and ELOVL1 expression (HR = 1.266, p < 0.001) were independent factors for OS of HCC patients." (PMID 35912257, 2022). "In men, a positive correlation was observed between the expression of ELOVL1 and SLC27A1, and SLC27A3 in the tumor core." (PMID 37239243, 2023). "In women, there was a positive correlation between ELOVL1 expression and SLC27A, SLC27A5, and SLC27A6 expression in the tumor core." (PMID 37239243, 2023). "In women, a positive correlation was observed between the expression of ELOVL1 and SLC27A4, SLC27A5, and SLC27A6 in the tumor core." (PMID 37239243, 2023). "Analysis of elongase expression showed that ELOVL1 and ELOVL7 expressions were lower in the GBM tumor than in the peritumoral area." (PMID 36291290, 2022). "As for the tumor heterogeneity, ELOVL1 was positively related to MATH (R = 0.15, P = 0.020), tumor ploidy (R = 0.12, P = 0.029), and LOH (R = 0.38, P = 0.001) in HCC." (PMID 35912257, 2022). "We showed that ELOVL1 and ELOVL7 expressions were lower in the GBM tumor than in the peritumoral area." (PMID 36291290, 2022). "The results showed that the expression of ELOVL1 and ELOVL7 in the GBM tumor was lower than in the peritumoral area." (PMID 36291290, 2022). "This study examines the expression of elongases ELOVL1, ELOVL2, ELOVL3, ELOVL4, ELOVL5, ELOVL6, and ELOVL7 in GBM tumor samples from 28 patients (16 men and 12 women), using a quantitative real-time polymerase chain reaction (qRT-PCR)." (PMID 36291290, 2022). "For instance, the treatment of EC cells with inhibitors of ACACA, ELOVL1, or FASN would directly test the hypothesis that increased de novo lipogenesis promotes tumor growth." (PMID 40244177, 2025). "Considering that we manipulated antigen-specific T cells (OT-I and Pmel-1), genetic deletion of Elovl1 could be applied to CAR T directed against solid tumour antigens, to sustain their persistence and at the same time sensitize the tumour to ICB treatment." (PMID 40065102, 2025). "The expression of CYP7A1, ELOVL1 and ACACA were higher in LIHC tumor tissues than normal tissues." (PMID 38584256, 2024). "Additionally, TIMER, CIBERSOR, and tumor immune dysfunction and exclusion (TIDE) were employed to evaluate the relationship between ELOVL1 and immune responses." (PMID 35912257, 2022). "ELOVL1 was positively correlated with PD-1 (PDCD1), CTLA4, LAG3, endothelial growth factors (VEGFs), and so on, which are the common immune checkpoints in the HCC tumor-immune microenvironment (TIME)." (PMID 35912257, 2022). "In contrast to previous findings, the results of the analysis of ELOVL1 expression suggest that these VLCFAs could originate from lipid uptake from outside the tumor and are not synthesized in situ." (PMID 40759952, 2025). "Although the expression of ELOVL1 was not statistically significant in para-tumor tissue compared to distant tissue, ELOVL4 catalyzes the synthesis of very long-chain fatty acids, and expression of this enzyme was also increased in the adjacent thyroid tissues with cancer examined." (PMID 39145825, 2025).
cancer (10 papers, 2016 to 2025). A tumor composed of atypical neoplastic, often pleomorphic cells that invade other tissues. "Nevertheless, the gene silencing results indicated that ELOVL1 is involved in cancer cell viability." (PMID 40759952, 2025). "Due to the higher level of VLCSFAs in cancer serum compared to control we determined the enzymatic index of ELOVL fatty acid elongase 1 (ELOVL1) in serum, estimated by calculating the product/precursor ratio of the fatty acids involved ((C24 + C22 + C20)/C18)." (PMID 39145825, 2025). "Concerning the ELOVL1, UGDH and HSP90AA1, studies only showed the correlation with cancer, and further exploration is needed to elucidate the underlying mechanisms." (PMID 36632140, 2023). "ELOVL1 has been suggested to be involved in various diseases, including cancers." (PMID 34257161, 2021). "This was accompanied by the upregulation of key enzymes involved in synthesis (FASN), elongation (ELOVL1,2,5,6,and 7), and desaturation (FADS1 and FADS2) in ovarian tissue compared to NC groups, implicating these pathways in cancer progression." (PMID 40371224, 2025). "ELOVL1 is positively related to MSI and HRD (R = 0.298967888875077, P = 1.71923786304186e-8) in eight cancers including HCC (R = 0.104455471439159, P = 0.0455298564418963)." (PMID 35912257, 2022). "For feasibility reasons, the initial screening identifying Elovl1 was conducted by introducing ovalbumin in the cancer cells, which is a non-endogenous antigen." (PMID 40065102, 2025). "However, it should be noted that the TNBC stained more strongly for ELOVL1 than hormone-positive, HER2-negative cancer tissue, which is mainly represented in our analysis (luminal A and luminal B subtypes)." (PMID 40759952, 2025). "We found that the ELOVL1 index was significantly higher in cancer tissue than in normal tissue." (PMID 40759952, 2025). "Interestingly, there were no obvious differences in ELOVL1 mRNA or protein levels between normal and cancer tissues." (PMID 40759952, 2025). "However, the results of these analyses show no obvious differences in ELOVL1 mRNA levels or protein levels between normal and cancer tissues." (PMID 40759952, 2025).
diseases of the central nervous system (1 paper, 2025). "These include genes involved in neurodegeneration (EIF5), diseases of the central nervous system (IPO13, ST3GAL3), tobacco addiction (CHRNB4, PSMA4), fatty acid metabolism (ACSBG1), and skin conditions (HYI, ELOVL1)." (PMID 40074595, 2025).
metabolic disease (1 paper, 2021). A congenital disorder (due to inherited enzyme abnormality) or acquired (due to failure of a metabolically important organ) disorder resulting from an abnormal metabolic process. "The proteins encoded by ELOVL1–7 genes are involved in the elongation of fatty acid chains of different lengths, and they play an important role in regulating the biological synthesis of lipids, fatty acid metabolism, and certain metabolic diseases." (PMID 33278864, 2021).
neurological disorder (1 paper, 2024). "ELOVL1 encodes an enzyme that elongates fatty acids and can cause a neurological disorder with ichthyotic keratoderma, spasticity, hypomyelination and dysmorphic features." (PMID 39152475, 2024).
of the colon (1 paper, 2023). "Choline acetyltransferase (ChAT) and ELOVL fatty acid elongase 1 (ELOVL1) have been implicated in diseases of the colon." (PMID 37569842, 2023).
ELOVL1 also shares sentences with these, for which no sentence is quoted: prostate carcinoma (2 papers); adrenoleukodystrophy (1); alcoholism (1); Alzheimer disease (1); Anxiety (1); Astigmatism (1); brain diseases (1); Cirrhosis (1); Corneal opacity (1); developmental delay (1); diabetic neuropathy (1); Dystonia (1); inherited diseases (1); leukemia (1); macular degeneration (1); Mitchell syndrome (1); movement disorder (1); Myoclonus (1); myopathy (1); neurocutaneous disorder (1); non-alcoholic fatty liver disease (1); Nystagmus (1); ovarian tumor (1); Photophobia (1); Skin rash (1); Stroke (1); triple-negative breast carcinoma (1).